LINC01537 (long independently transcribed non-coding RNA 1537)
Synonyms: h-Hilnc; RP11-169D4.1-001
Gene: Long non-coding RNA gene on chromosome 11 (72,570,645 to 72,573,229, forward strand). Ensembl gene ENSG00000227467.
Diseases named in the same sentence as LINC01537 in open-access papers:
LINC01537 is named in the same sentence as 5 diseases in open-access papers, as found by Europe PMC text mining. Sharing a sentence is not in itself a finding about the gene and the disease. The quoted sentences say what the papers report.
lung carcinoma (3 papers, 2019 to 2022). "We found that LINC01537 functions as a regulator of energy metabolism to suppress lung cancer development via PDE2A, underlying a mechanism that LINC01537 stabilizes PDE2A mRNA via RNA–RNA interaction." (PMID 31374807, 2019). "Thus it is possible that a physical interaction between PDE2A and LINC01537 exists, which has been observed in lung cancer." (PMID 36054420, 2022). "Furthermore, LINC01537 overexpression induced lung cancer cells stop in the period of G0/G1 and accelerate cell apoptosis." (PMID 31374807, 2019). "Furthermore, downregulated LINC01537 was observed in lung cancer in the eastern samples with a margin at the edge of significance (p = 0.063)." (PMID 31374807, 2019). "The downregulation of LINC01537 and TMEM106A was observed in lung cancer development, which was involved in tumor metabolic reprogramming or EMT." (PMID 35433477, 2022). "LINC01537 is located on human chromosome 11q13.4, a locus with high frequency of copy number change in LUAD, which may be a reason for LINC01537 abnormal expression in lung cancer." (PMID 31374807, 2019).
gastric cancer (1 paper, 2022). A primary or metastatic malignant neoplasm involving the stomach. "Our study demonstrated that a high expression level of LINC01537 is associated with a poor prognosis in the gastric cancer cohort in the TCGA database." (PMID 36358656, 2022).
squamous carcinomas (1 paper, 2025). "Among the most significantly downregulated transcripts in later stage tumors are DEFB132 (a defensin involved in innate immunity), C14orf180 (an integral plasma membrane protein), TMEM252 (an integral plasma membrane protein), and LINC01537, an LncRNA associated with squamous carcinomas." (PMID 41224793, 2025).
tumor (5 papers, 2019 to 2025). "LINC01537 overexpression led to step-down cell proliferation rate, low tumor formation rate in vitro, and little tumor growth in vivo." (PMID 31374807, 2019). "Expressions of LINC01537 in subcutaneous tumor and liver metastasis were detected via RT- PCR." (PMID 36358656, 2022). "LINC01537 acts as a tumor suppressor to prohibit tumor cell growth, migration, and invasion, by promoting apoptosis and to regulating cell cycle, further supporting the hypothesis that it could be a potential therapeutic target." (PMID 31374807, 2019). "Therefore, these seven mRNAs, similar to LINC01537, might be tumor suppressors in digestive glands." (PMID 36054420, 2022).
cancer (1 paper, 2019). A tumor composed of atypical neoplastic, often pleomorphic cells that invade other tissues. "To further reveal the molecular mechanism of how LINC01537 regulates cancer development, we tentatively verified that the lncRNA can increase PDE2A expression by RNA–RNA interaction." (PMID 31374807, 2019). "In addition, cancer cells generally expressed lower LINC01537 than noncancer cells." (PMID 31374807, 2019).